STIM1 (stromal interaction molecule 1)
Diseases named in the same sentence as STIM1 in open-access papers (continued):
Sharing a sentence is not in itself a finding about the gene and the disease.
glioblastoma (21 papers, 2013 to 2024). The most malignant astrocytic tumor (WHO grade IV). "Higher levels of Stim1 and Orai1 mRNA have been detected in human glioblastoma, where they are associated to the higher amplitude of thapsigargin-induced SOCE." (PMID 24603752, 2014). "STIM1 loss of function was performed on U251 cells, derived from grade IV astrocytomas-glioblastoma multiforme with a lentvirus-mediated short harpin RNA (shRNA) method." (PMID 23578185, 2013). "Found up-regulated in glioblastoma multiforme (GBM), STIM1 and Orai1 are positively associated with GBM invasiveness." (PMID 32599788, 2020). "Electrophysiological recordings in glioblastoma cells and in astrocytes demonstrated that STIM1 and Orai1-mediated SOCE results in highly inward rectifying Ca2+ currents." (PMID 33036292, 2020). "STIM1 and Orai1 play a significant role in human glioblastoma or glioblastoma multiforme (GBM) cells, a form of aggressive brain malignant tumor which originates from glial cells and astrocytes." (PMID 33333945, 2020). "In glioblastoma multiforme, STIM1 and Orai1 knockdown decreased cancer cell invasion and proliferation, respectively." (PMID 32599788, 2020). "The Ca2+ sensor STIM1 is overexpressed in different carcinomas, e.g., glioblastoma, cervix, breast, lung, liver, melanoma and colon." (PMID 32733237, 2020). "The abolition of STIM1 also prevents the cell proliferation and induces G0/G1 phase arrest of human glioblastoma cells." (PMID 32733237, 2020). "STIM1 silencing slowed cell proliferation by arresting cell cycle at G0/G1 phase in glioblastoma cell lines, attributed to the regulation of the p21, cyclin D1, and CDK4." (PMID 31252656, 2019). "For example, downregulation of STIM1 expression inhibited glioblastoma U251 cell proliferation by inducing cell cycle arrest in the G0/G1 phase through regulation of p21Waf /Cip, cyclin D1 and CDK4." (PMID 31564210, 2019). "The pharmacological blockade of SOCE did not affect proliferation also in primary cultures of metastatic RCC cells and of glioblastoma cells, although Stim1 and Orai1 promoted migration and invasion in the latter." (PMID 30123430, 2018). "Our results showed that specific downregulation of STIM1 inhibited human glioblastoma cell proliferation and induced G0/G1 phase cell cycle arrest by increasing expression of p21Waf1/cip1 and decreasing expression of Cyclin D1-CDK4." (PMID 23578185, 2013). "In the present study, we found that expression of STIM1 protein was higher in U251 and U87 glioblastoma multiforme (both Grade IV) lines than in U373 astrocytoma (Grade III), particularly higher in U251 cells." (PMID 23578185, 2013). "The biological impacts after knock down of STIM1 on glioblastoma cells were investigated in vitro and in vivo." (PMID 23578185, 2013). "In conclusion, we report that STIM1 is expressed in human glioma cell lines derived from a high-grade glioblastoma." (PMID 23578185, 2013). "Expression of STIM1 protein in a panel of human glioblastoma cell lines (U251, U87 and U373) in different transformation level were evaluated by Western blot method." (PMID 23578185, 2013). "Interestingly, another report revealed that both STIM1 and Orai1 are essential for the survival and proliferation of glioblastoma cell lines." (PMID 33333945, 2020). "Similarly, knockdown of STIM1 or Orai1 in rat and human glioblastoma cells inhibited tumor cell proliferation and promoted apoptosis." (PMID 29783744, 2018). "Our findings confirm STIM1 as a rational therapeutic target in human glioblastoma, and also indicate that lentivirus-mediated STIM1 silencing is a promising therapeutic strategy for human glioblastoma." (PMID 23578185, 2013). "However, subsequent studies revealed a potential role of STIM1 as an oncogene because it is up-regulated in several human cancers, such as breast cancer, glioblastoma and cervical cancer." (PMID 23578185, 2013).
glioblastoma (continued). "However, subsequent study of the signaling pathway which regulates STIM1 function in glioblastoma still needs to be elucidated." (PMID 23578185, 2013). "Moreover, the larger magnitude of agonist-induced SOCE in the human glioblastoma cell line U251 was not accompanied by the up-regulation of the mRNAs encoding for Stim1 and Orai1." (PMID 30123430, 2018). "Thus, our findings illustrate the biological significance of STIM1 in tumorigenesis of glioma, and provide evidences that STIM1 may be a potential therapeutic target for human glioblastoma." (PMID 23578185, 2013). "STIM1 and ORAI1 have been shown to be involved in Ca2+ signaling in both astroglia and glioblastoma cells." (PMID 33424550, 2020). "The silencing of STIM1 or Orai1 was shown to reduce SOCE and CRAC currents in human glioblastoma cells." (PMID 33424550, 2020). "Therefore, STIM1 may serve as a therapeutic target for human glioblastoma." (PMID 23578185, 2013). "However, the role of STIM1 in regulating tumorigenesis of human glioblastoma still remains unclear." (PMID 23578185, 2013). "The low expression of STIM1 and STIM2 drives glioblastoma (GBM) progression." (PMID 39272139, 2024). "Both ORAI1 and STIM-1 are upregulated in primary human cell lines obtained from surgical samples of glioblastoma multiforme compared to non-tumor human astrocytes." (PMID 33122991, 2020). "The complex regulation of the Ca2+ machinery under pathological conditions is further corroborated by the finding that the higher amplitude of SOCE in the human glioblastoma cell line U251 is not mirrored by the up-regulation of Orai1 and Stim1 transcripts." (PMID 24603752, 2014). "Several studies have shown that STIM1 is overexpressed in human glioblastoma, but the molecular mechanism was not identified." (PMID 23578185, 2013). "While small interfering RNA (siRNA)-mediated silencing of ORAI1 (but not STIM1) marginally reduces cell proliferation, silencing of both ORAI1 and STIM1 dramatically reduces invasion of glioblastoma cells." (PMID 30691160, 2019).
severe combined immunodeficiency (17 papers, 2013 to 2025). Severe combined immunodeficiency (SCID) comprises a group of rare monogenic primary immunodeficiency disorders characterized by a lack of functional peripheral T lymphocytes resulting in early-onset severe respiratory infections and failure to thrive. "Deficiency of stromal interaction molecule 1 (STIM1) results in combined immunodeficiency accompanied by extra-immunological findings like enamel defects and myopathy." (PMID 38578569, 2024). "Mutations in the Orai1 or STIM1 genes abolish SOCE leading to combined immunodeficiency (CID), muscular hypotonia, and anhidrotic ectodermal dysplasia." (PMID 33650027, 2021). "In contrast, LOF mutations affecting STIM1 results in a combined immunodeficiency (CID) accompanied by autoimmunity, ectodermal dysplasia presented as dental enamel defects and anhydrosis, and non-progressive myopathy characterized by muscular hypotonia and partial iris hypoplasia causing mydriasis." (PMID 38578569, 2024). "Mutations in the genes encoding for Stim1 and Orai1 have long been associated to the development of rare, but lethal, inherited immunodeficiency disorders, such as severe combined immunodeficiency (SCID), where the abrogation of SOCE compromises immune system functions." (PMID 24603752, 2014). "Similarly, mutations in the gene encoding the Ca2+ release-activated Ca2+ (CRAC) channel, ORAI1, and its activator stromal interaction molecule 1 (STIM1), are implicated in severe combined immunodeficiency (SCID), tubular aggregate myopathy (TAM), and Stormorken syndrome." (PMID 40103710, 2025). "Both Orai1 and STIM1 are critical for T cell immunity as evident from loss of function mutations of Orai1 or STIM1 which eliminate SOCE and result in impaired cytokine production, abrogated T cell activation, and severe combined immunodeficiency in patients." (PMID 36467682, 2022). "Loss of functional ORAI1 or STIM1 in humans leads to severe combined immunodeficiency (SCID)." (PMID 26052328, 2015). "Recessive STIM1 and ORAI1 loss-of-function (LoF) mutations resulting in insufficient SOCE cause CRAC channelopathies characterized by severe combined immunodeficiency (SCID) involving recurrent and chronic infections, autoimmunity, muscular hypotonia, ectodermal dysplasia, anhidrosis, and mydriasis." (PMID 33250786, 2020).
colon carcinoma (15 papers, 2013 to 2023). "STIM1 is upregulated in various human malignancies, including liver, breast, cervical, and colon cancers." (PMID 36677874, 2023). "While SigmaR1 and STIM1 interact directly in HEK 293 cells, in breast and colon cancer cells, this receptor associates directly with SK3 and triggers a close association of Orai1 and SK3." (PMID 33333945, 2020). "Taken together, these data suggest that SOCE induced by STIM1/Orai1/TRPC1 plays a role in SK3-dependent colon cancer cell migration." (PMID 27102434, 2016). "Furthermore, Cav-1 was reported to further contribute to STIM1/TRPC1/Orai1/SK3 complex formation in colon cancer." (PMID 35327543, 2022). "Moreover, miRNA-185 modulates the metastatic properties of colon cancer cells by targeting STIM1." (PMID 36677874, 2023). "Accordingly, both technologies reported the overexpression of STIM1, MBP, SEPTIN9, and SEPTIN10 and the downregulation of CRACR2A, ORMDL3, SARAF, SEPTIN3, and SEPTIN6 in colon cancer cells." (PMID 36900391, 2023). "In colon cancer cells, the recruitment of Orai1-TRPC1 channels into lipid rafts containing SK3 channels is further triggered by STIM1." (PMID 33333945, 2020). "In summary, we demonstrated for the first time that HSP27 is a chaperone that stabilizes STIM1 of the SOCE, and its targeting resulted in arrest of G2/M transition, leading to decreased cancer proliferation, migration and invasion of colon cancer cells." (PMID 30544747, 2018). "Recently, human colon cancer cells have been shown to present an increase of SOCE, related to an increase in TRPC1, Orai1, Orai2, Orai3 and STIM1 expressions." (PMID 27102434, 2016). "In contrast, colon cancer cell migration is manifested through the formation of a triple channel complex of the TRPC1/Orai1/SK3 channels in cholesterol-rich regions, which is further facilitated by STIM1." (PMID 36612099, 2022). "Similarly, colon cancer cell growth is driven by an interplay of SK3 and Orai1 which is further supported by STIM1 and TRPC1." (PMID 35327543, 2022). "Since we observed that STIM1 binding to Orai1 reduces the co-localization with SK3 in HEK293 cells, it might be interesting to determine whether and how endogenous as well as overexpressed STIM1 affect the co-localization and interplay of SK3 and Orai1 in colon cancer cells." (PMID 36612099, 2022). "Interestingly, we reported that colon cancer HT29 cells display enhanced STIM1 expression along decreased STIM2 expression relative to normal NCM460 colonic cells, thus, resulting in enhanced STIM1 to STIM2 ratio in cancer cells." (PMID 30642111, 2019). "In fact, increased expression of molecular players involved in SOCE, particularly Orai1 and Stim1, may not be enough to sustain Ca2+ in colon cancer cells." (PMID 28903423, 2017). "Previous reports on breast and colon cancer cells revealed enhanced Ca2+ levels due to an interplay of SK3 and Orai1, independent of STIM1." (PMID 34944977, 2021).
neuroblastoma (15 papers, 2018 to 2025). Neuroblastoma (NB) is the most common solid, extracranial childhood tumor. "The real impact of the loss of STIM1 at the cellular level was studied by knocking-out STIM1 gene in the neuroblastoma cell line SH-SY5Y by genome editing with CRISPR/Cas9." (PMID 32916960, 2020). "In this regard, the presenilin-1 (PSEN1)-associated γ-secretase interacts with STIM1 in human neuroblastoma SH-SY5Y cells, familial Alzheimer’s disease (FAD) patient skin fibroblasts, and mouse primary cortical neurons." (PMID 30088035, 2018). "Of note, muscarinic acetylcholine receptors have been previously associated with STIM1/Orai1‐mediated SOCE in neuroblastoma cells; however, whether this is also the case in the heart remains to be determined." (PMID 35179826, 2022). "It was shown that STIM1 expression was unaltered in the substantia nigra of PD patients and that STIM1 silencing decreased the viability of human neuroblastoma SH-SY5Y cells." (PMID 33809535, 2021). "The loss of STIM1 and STIM2 proteins was also observed in SH-SY5Y neuroblastoma cells that had low levels of the proteasome subunit β type 5." (PMID 33424550, 2020). "Endogenous PS1 and STIM1 have been shown to interact in human SH-SY5Y neuroblastoma cells and mouse primary cortical neurons." (PMID 33424550, 2020). "Finally, to consolidate the latest results, we used the neuroblastoma NG115-401L cell line that expresses a scarce amount of STIM1." (PMID 31973006, 2020). "Consequently, STIM1 in 401L neuroblastoma cells provided protection against ER stress and mitochondrial oxidative stress causing cell death." (PMID 33424550, 2020). "In human neuroblastoma cells, the expression of the N-terminal fragment of mHtt (Htt138Q-1exon) is sufficient to cause a HD pathological phenotype, as it induces an increase of SOCE that requires STIM1 in this in vitro model." (PMID 29623030, 2018). "In human neuroblastoma cells, the HD pathological phenotype was mediated by expression of the N-terminal fragment of mHTT, which increased SOCE in a STIM1-dependent manner." (PMID 31075835, 2019). "Similar results were observed in primary mouse cultures of MSNs and in mouse neuroblastoma cells, where the N-terminal HTT fragment enhanced SOCE through STIM1 and Orai1 or TRPC1." (PMID 31075835, 2019). "In mouse primary cortical neurons and human neuroblastoma SH-SY5Y cells, FAD PS1 increased γ-secretase cleavage of the STIM1 transmembrane domain, thus attenuating SOCE, which in turn destabilized dendritic spines." (PMID 31075835, 2019). "Most importantly, this study demonstrated that in SH-SY5Y neuroblastoma cells, MPP+ treatment decreased TRPC1 expression, TRPC1 interaction with the SOCE modulator stromal interaction molecule 1 (STIM1), and Ca2+ entry into the cells." (PMID 30082759, 2018). "In order to study the role of STIM1 in neurodegeneration, we followed a well-established protocol to trigger differentiation of SH-SY5Y neuroblastoma cells differentiation in vitro." (PMID 30088035, 2018). "In neuroblastoma SH-SY5Y cells and in familial Alzheimer’s disease patient skin fibroblasts, STIM1 is cleaved at the transmembrane domain by the presenilin-1-associated γ-secretase, leading to dysregulation of Ca2+ homeostasis." (PMID 30088035, 2018). "Moreover, expression of mutant HTT in mouse neuroblastoma and MSNs showed enhanced SOCE activation, which was reversed by RNAi knockdown of Orai1, TRPC1, or STIM1." (PMID 40169779, 2025). "Although the STIM1 KD did not affect the VGC entry in VSMCs at a steady state (without store depletion), the STIM1-KO was reported to increase VGC entry in differentiated human neuroblastoma SH-SY5Y under the same conditions." (PMID 36499137, 2022). "STIM1 knockout in a neuroblastoma cell line showed that although STIM1 was not required for neuronal cell differentiation, it was required for cell survival." (PMID 35821821, 2022).
neuroblastoma (continued). "The lack of STIM1 in differentiated neuroblastoma cells triggered a pathological increase in Ca2+ entry through L-type voltage-operated Ca2+ channels in response to depolarization, in agreement with the modulating role of STIM1 on these channels." (PMID 30669311, 2019). "It has been reported earlier that STIM1 acts as a negative regulator of endogenous or overexpressed L-type calcium channels upon ER calcium store depletion in arterial smooth muscle cells (A7r5 VSMCs), cortical neurons, Jurkat T cells, HEK293 cells, and neuroblastoma Neuro2a." (PMID 36499137, 2022). "Similar findings were obtained in mouse neuroblastoma cells and in primary culture of mouse MSNs, where lentiviral expression of Htt138Q-1exon results in enhanced SOCE through the involvement of the sensor STIM1 and of both TRPC1- and Orai1 subunits forming a heteromeric channel." (PMID 29623030, 2018). "With STIM1-deficient cells, we demonstrate here that STIM1 is not directly involved in the differentiation of neuroblastoma SH-SY5Y cells triggered by RA + BDNF, although STIM1 is essential to sustain cell viability in differentiated cells." (PMID 30088035, 2018).
heart failure (14 papers, 2017 to 2025). Inability of the heart to pump blood at an adequate rate to meet tissue metabolic requirements. "In studies in transgenic mice, an association was found between overexpression of STIM1, which enhanced calcium entry following intracellular store depletion, and increased diastolic calcium levels and enhanced susceptibility toward sudden death and heart failure with hypertrophy." (PMID 28126709, 2017). "Previous studies have demonstrated that cardiomyocyte-specific STIM1 suppression in mice results in age-dependent cardiomyopathy and heart failure in adults, whereas severe heart failure was evident during embryogenesis in zebrafish with Orai1 suppression." (PMID 32086252, 2020). "It was also demonstrated that cardiac stromal interaction molecule 1 (STIM1) inhibition promoted heart failure by repressing mTORC2." (PMID 30021848, 2018). "In a mouse model of heart failure, they demonstrated that PS improved cardiac function and rhythmicity by stabilizing ryanodine receptor 2 (RyR2)-mediated calcium release from the sarcoplasmic reticulum and inhibiting STIM1-mediated calcium entry." (PMID 40970182, 2025). "This suggests that a reduction of STIM1 in UP patients may have a correlation with the development of cardiac failure." (PMID 38577622, 2024). "A previous study found that over-expression of STIM1 exhibited sudden death and heart failure." (PMID 35303866, 2022). "Moreover, mice with cardiomyocyte over‐expression of STIM1 exhibit increased incidence of sudden cardiac death, and those that survive develop hypertrophy and heart failure." (PMID 35179826, 2022). "The authors speculated that STIM1 activity and SOCE increase during heart failure because of a reduction in NO bioavailability; however, this has yet to be determined." (PMID 35821821, 2022). "Ventricular fibroblasts derived from patients with heart failure exhibited increased Orai1, but similar STIM1 protein expression levels compared to those of non-failing hearts." (PMID 35008591, 2021). "The autopsies of STIM1+/–TAC mice that died shortly after surgery showed no remarkable perivascular edema in the lungs or ventricular dilation indicative of heart failure." (PMID 29145451, 2017). "For instance, the STIM1 protein was observed to be present in reduced quantities in individuals with UP, and prior research indicates that silencing of Stim1 augments the activity of the anti-hypertrophic and pro-apoptotic molecule GSK-3β, which may accelerate the progression towards heart failure." (PMID 38577622, 2024). "Furthermore, the autopsies of STIM1+/–TAC mice that died shortly after surgery showed no remarkable perivascular edema in the lungs or ventricular dilation indicative of heart failure." (PMID 29145451, 2017).